XIST (X inactive specific transcript)
Diseases named in the same sentence as XIST in open-access papers (continued):
Sharing a sentence is not in itself a finding about the gene and the disease.
cancer (continued). "To date, the previous studies imply that XIST may be a cancer-promoting factor in RB, yet the role and molecular mechanism of XIST in the tumorigenesis and development of RB have not been fully elucidated." (PMID 33942699, 2021). "It seems that XIST gene is upregulated in a variety of non-sex-related tumors in both humans and mice, whereas it might be lost in some female cancers." (PMID 28837144, 2017). "XIST was selected in the male vs. female classification model for 14 of 17 cancer types, but was not selected in any of the male vs. female analyses in normal samples, suggesting that differences in XIST expression between male and female tissues emerge during oncogenesis." (PMID 26755347, 2016). "Notably, we detected aberrant expression of XIST, the essential X-chromosome-inactivation lncRNA that is not normally expressed in males, and upregulation of genes known to escape X-inactivation, including male-biased cancer-related genes KDM6A, DDX3X, KDM5C, and ZRSR2." (PMID 42070154, 2026). "The expression levels of lncRNA CCAT1, but not XIST, were meaningfully increased in the plasma-derived exosomes of CRC patients compared to non-cancer individuals (p= 0.001, 0.083 respectively)." (PMID 40028475, 2025). "XIST, MALAT1, NEAT1, and LINC00240 up-regulated lncRNA were predicted to bind to hsa-mir-124-3p and promoted the proliferation and metastasis of other cancers by modulating hsa-mir-124-3p, but there are no related studies in CCRCC." (PMID 36531222, 2022).
cardiovascular diseases (7 papers, 2020 to 2026). "The roles of XIST-mediated miRNA sequestration in cardiovascular disease appears to be dependent on the pathological context and experimental model and require more rigorous examination." (PMID 41601966, 2026). "However, there is no further information about the role of XIST in cardiovascular disease or other molecular mechanisms." (PMID 32315985, 2020).
digestive system tumors (4 papers, 2018 to 2025). "In subgroup analysis, it revealed that lncRNA XIST overexpression was significantly associated with worse OS in digestive system tumors (HR = 1.67, 95% CI 1.11–2.51, p = 0.031)." (PMID 29556138, 2018). "The association between lncRNA XIST overexpression and worse OS was statistically significant in digestive system tumors (HR = 1.67, 95% CI 1.11–2.51, p = 0.014, random-effect)." (PMID 29556138, 2018). "In fact, the conditional knockout of XIST leads to a greater development of larger gastrointestinal tumors under stress than does the wild type." (PMID 40407589, 2025). "Our meta-analysis showed elevated XIST expression levels in digestive system tumors predicted worse prognosis than in non-digestive system tumors for the first time." (PMID 29752340, 2018). "Additionally, we found that XIST was more valuable in digestive system tumors (pooled HR = 2.24, 95% CI: 1.73–2.92) than in non-digestive system tumors (pooled HR = 1.22, 95% CI: 0.60–2.45)." (PMID 29752340, 2018).
blood cancer (3 papers, 2018 to 2023). "have demonstrated that deleting XIST is sufficient to induce an aggressive, lethal blood cancer in mice." (PMID 38148658, 2023). "Deletion of XIST in blood cells of female mice results in X reactivation and blood neoplasms." (PMID 30281678, 2018).
cardiac diseases (2 papers, 2020 to 2024). "It has been shown that XIST is associated with a variety of cardiac diseases." (PMID 38699233, 2024). "It has been frequently reported that the lncRNA XIST interacts with miRNAs to regulate cell function in different diseases, including cardiac diseases." (PMID 32315985, 2020). "Thus, modulation of XIST may represent a novel approach for interventional treatment of heart disease." (PMID 32315985, 2020).
digestive system cancer (2 papers, 2018 to 2021). A primary or metastatic malignant neoplasm involving any part of the digestive system. "Among all 6 studies, reported XIST as the oncogene and evaluated the association between XIST expression levels and OS, 4 studies explored the digestive system carcinoma and other 2 studies explored the non-digestive system carcinoma." (PMID 29568404, 2018).
infection (2 papers, 2017 to 2024). The state of being infected such as from the introduction of a foreign agent such as serum, vaccine, antigenic substance or organism. "Moreover, we observed that XIST expression is up-regulated in non-CF cells during infection at 4 and 6 h (FC > 2)." (PMID 28611953, 2017).
neurodegenerative disease (2 papers, 2022 to 2025). A disorder of the central nervous system characterized by gradual and progressive loss of neural tissue and neurologic function. "An increasing body of evidence suggests that XIST may play a role in the onset and progression of autoimmune and neurodegenerative diseases, either as a regulator of miRNA-mRNA interactions or through other mechanisms." (PMID 40407589, 2025).
renal diseases (1 paper, 2023). "Among these, PVT1 and XIST have a common mechanism on multiple kidney diseases, the first increasing the expression of extracellular matrix proteins through the TGFB and the second inducing apoptosis." (PMID 37190024, 2023). "In addition, it is noteworthy that by analyzing lncRNA studies performed on renal diseases, we can identify six lncRNAs involved in more than one type of renal disease, in particular PVT1, TUG1, NEAT1, MALAT1, XIST, and H19." (PMID 37190024, 2023).
XIST also shares sentences with these, for which no sentence is quoted: acute lung injury (4 papers); acute myocardial infarction (4); Cerebral ischemia (3); myeloproliferative neoplasm (3); coronary artery disease (2); germ cell tumor (2); heart failure (2); hematologic cancer (2); neurological diseases (2); polycystic ovary syndrome (2); Sjögren’s syndrome (2); triple X syndrome (2); uveal melanoma (2); Abdominal obesity (1); acute lymphoblastic leukemia (1); adenoma (1); age-related macular degeneration (1); aneurysm (1); bipolar disorder (1); brain cancer (1); brain tumours (1); Calcium oxalate nephrolithiasis (1); cervical squamous cell carcinoma (1); chromosome abnormality disorders (1); Chronic Hepatitis B- (1); clear cell renal cell cancer (1); collecting duct carcinoma of the kidney (1); complex regional pain syndrome (1); Deep Venous Thrombosis (1); diabetic cardiomyopathy (1).
A further 41 diseases each share a sentence with XIST in 1 paper.